CTHRC1 (collagen triple helix repeat containing 1)
Diseases named in the same sentence as CTHRC1 in open-access papers (continued):
Sharing a sentence is not in itself a finding about the gene and the disease.
pancreatic cancer (23 papers, 2010 to 2025). "In conclusion, CTHRC1 is highly expressed in CAFs of pancreatic cancer and is associated with the poor prognosis of patients." (PMID 40751418, 2025). "In this study, we found that CTHRC1 is highly expressed in the cancer‐associated fibroblasts (CAFs) of pancreatic cancer and is associated with poor prognosis in patients." (PMID 40751418, 2025). "Overexpression of CTHRC1 that encodes for a secretary protein involved in vascular remodeling through limiting collagen matrix deposition, has been associated with pancreatic cancer cells migration and metastasis, and melanoma invasiveness." (PMID 27144525, 2016). "Here we found that CTHRC1 is closely associated with tumor vascularization in pancreatic cancers." (PMID 27686285, 2016). "Other novel FTSEC biomarkers that are overexpressed in HGSOCs include CELSR3, an atypical cadherin; ABCC3, an ABC transport protein implicated in drug resistance; and CTHRC1, a secreted protein shown to be a candidate biomarker for breast and pancreatic cancer." (PMID 24070420, 2013). "We employed multi‐omics analysis combined with cellular and animal experiments to examine the association between CTHRC1 and the LIF/STAT3 pathway in pancreatic cancer clinical specimens." (PMID 40751418, 2025). "CAFs with CTHRC1 knockdown and pancreatic cancer cells (Aspc‐1) were co‐injected into the mouse pancreas at a 1:3 ratio." (PMID 40751418, 2025). "The in vivo results showed that, compared to the control group, CTHRC1 knockdown CAFs significantly inhibited the proliferation of pancreatic cancer cells, and tumor volume and weight were significantly smaller than in the control group." (PMID 40751418, 2025). "Western Blot and q‐PCR further confirmed that CTHRC1 was highly expressed in CAFs, which was significantly higher than that in pancreatic cancer cells and pancreatic stellate cells." (PMID 40751418, 2025). "Additional coculture experiments using HPSC‐CM, CTHRC1‐knockdown CAFs‐CM, and CTHRC1‐overexpressing CAFs‐CM consistently confirmed CTHRC1's positive regulation of STAT3 activation in pancreatic cancer cells." (PMID 40751418, 2025). "This study uncovers the biological mechanism of CTHRC1 in CAFs in pancreatic cancer, providing new strategies for the treatment of pancreatic cancer." (PMID 40751418, 2025). "Given the abundance of CAFs in the pancreatic cancer microenvironment, these findings indicate that CTHRC1 likely drives tumor progression." (PMID 40751418, 2025). "To further investigate the regulatory role of CTHRC1 in CAFs on pancreatic cancer progression in vivo, we established a mouse orthotopic pancreatic cancer xenograft model." (PMID 40751418, 2025). "In vitro experiments have confirmed that CTHRC1 in CAFs promotes the proliferation, migration, and invasion of pancreatic cancer cells." (PMID 40751418, 2025). "Colony formation and Transwell migration assays further revealed that genetic reconstitution of CTHRC1‐overexpressing CAFs restored their ability to promote pancreatic cancer cell proliferation and migration." (PMID 40751418, 2025). "Functionally, we observed that CTHRC1 in CAFs promotes the proliferation, migration, and invasion of pancreatic cancer cells both in vitro and in vivo." (PMID 40751418, 2025). "The results showed that CTHRC1 knockdown in CAFs significantly inhibited the proliferation and migration of pancreatic cancer cells." (PMID 40751418, 2025). "Double‐labeled immunofluorescence staining of human pancreatic cancer tissues showed that CTHRC1 was significantly colocalized with CAFs in pancreatic cancer tissues." (PMID 40751418, 2025). "Subsequently, CAFs‐CM with CTHRC1 knockdown or overexpression were cocultured with pancreatic cancer cells, and after 24 h, we extracted the cell proteins to detect the activation of the STAT3 signaling pathway." (PMID 40751418, 2025).
pancreatic cancer (continued). "In vivo experiments further validated its pro‐tumorigenic role, confirming CTHRC1 as a driver of pancreatic cancer progression and highlighting its potential as a therapeutic target." (PMID 40751418, 2025). "In mechanistic studies, RNA sequencing revealed that CTHRC1 promotes the proliferation and migration of pancreatic cancer cells through the LIF‐mediated STAT3 axis." (PMID 40751418, 2025). "CCK‐8 proliferation assays and Transwell migration assays were employed to examine the effects of STAT3 inhibition on pancreatic cancer cell proliferation and migratory capacity under CTHRC1‐overexpressing CAFs‐CM stimulation." (PMID 40751418, 2025). "On the other hand, CAFs overexpressing CTHRC1 significantly increased the phosphorylation level of STAT3 in pancreatic cancer cells and promoted the activation of the STAT3 signaling pathway." (PMID 40751418, 2025). "Then, we cocultured CAFs‐CM overexpressing CTHRC1 with pancreatic cancer cells and added the LIF inhibitor EC330 at various concentrations." (PMID 40751418, 2025). "This study, through single‐cell sequencing bioinformatics analysis, first identified CTHRC1 as specifically overexpressed in pancreatic cancer CAFs, with its expression significantly correlated to poor patient prognosis." (PMID 40751418, 2025). "CTHRC1 in CAFs promotes the growth and metastasis of pancreatic cancer cells through the LIF/STAT3 signaling pathway." (PMID 40751418, 2025). "Compared with controls, CTHRC1‐knockdown CAFs significantly suppressed spherogenesis in Panc‐1 cells, indicating that CAF‐derived CTHRC1 promotes self‐renewal capacity and stemness maintenance in pancreatic cancer cells." (PMID 40751418, 2025). "Second, our analysis results from TCGA and GEPIA databases showed that CTHRC1 was significantly overexpressed in pancreatic cancer, which was significantly different from other tumors." (PMID 40751418, 2025). "After knocking down CTHRC1 in CAFs, the proliferation, migration, invasion, tumor growth, and metastasis of pancreatic cancer cells were significantly inhibited." (PMID 40751418, 2025). "Secondly, we investigated the regulatory role of CTHRC1 in CAFs on the migration and invasion of pancreatic cancer cells." (PMID 40751418, 2025). "Our current study demonstrates that in pancreatic cancer, CTHRC1+ CAFs primarily rely on the LIF/STAT3 signaling pathway to promote pancreatic cancer cell growth and metastasis." (PMID 40751418, 2025). "The influence of CTHRC1 was further tested in subcutaneous and orthotopic human pancreatic cancer mouse models to demonstrate proof of concept." (PMID 37444482, 2023). "This study elucidates PSC activation as the central mechanism underlying the pro-tumoral effects of CTHRC1 and suggests that future studies on CTHRC1 as a potential therapeutic target for pancreatic cancer are warranted." (PMID 37444482, 2023). "The RNA-sequencing data retrieved from the datasets showed the mRNA expression of CTHRC1 in pancreatic tumor tissue was significantly higher than in the paired adjacent non-tumor tissue samples." (PMID 37444482, 2023). "This study showed that CTHRC1, a secreted protein that is highly expressed in pancreatic tumor tissue, has a critical role in ECM remodeling through PSC activation and CAF differentiation." (PMID 37444482, 2023). "Two programs (TCGA and CPTAC) containing relevant pancreatic cancer survival data and CTHRC1 tumor expression data were retrieved from the cBioPortal." (PMID 37444482, 2023). "The inhibition of CTHRC1 as a therapeutic strategy for the treatment of pancreatic cancer warrants further investigation." (PMID 37444482, 2023). "Two datasets (GSE93326 and GSE164665) met the inclusion criteria and were used for the comparison of CTHRC1 mRNA expression between paired pancreatic cancer cells (epithelium) and stromal cells." (PMID 37444482, 2023).
pancreatic cancer (continued). "[METHODS AND RESULTS] The analyses of the publicly available pancreatic cancer patient data revealed that CTHRC1 is mainly expressed in cancer stroma and highly correlated with ECM-related genes." (PMID 37444482, 2023). "Compared to a direct culture of pancreatic cancer cells with PBS/CTHRC1, the treatment of pancreatic cancer cells with PSC-conditioned media obtained from PBS/CTHRC1-treated PSCs resulted in a significantly higher cancer cell proliferation." (PMID 37444482, 2023). "CTHRC1 (collagen triple-helix repeat-containing 1), a protein secreted during the tissue-repair process, is highly expressed in several malignant tumors, including pancreatic cancer." (PMID 27686285, 2016). "Here, we demonstrated that in the pancreatic tumor microenvironment, the CTHRC1/Ang-2/TEM axis can be a target for anti-tumor therapy by reducing tumor angiogenesis." (PMID 27686285, 2016). "We recently showed that CTHRC1 has an important role in the progression and metastasis of pancreatic cancer." (PMID 27686285, 2016). "The similar effects of CTHRC1 in HCC and pancreatic cancer suggest that CTHRC1 is an important effector for tumor invasion." (PMID 23922981, 2013). "The best three single-gene discriminators are KRT17, COL10A1 and CTHRC1 for pancreatic cancer, having the same classification accuracy, 93.6% on the training set and 88.5% and 80.4%, 84.6% and 73.2%, and 84.6% and 85.7% on the two test sets, respectively." (PMID 21060876, 2010). "Additionally, we used clone formation and Transwell migration assays to explore the effects on proliferation and migration in pancreatic cancer cells after CAFs with CTHRC1 knockdown were reconstructed and overexpressed." (PMID 40751418, 2025). "Similarly, we also examined the effect of adding the LIF inhibitor to CAFs‐CM overexpressing CTHRC1 on the proliferation and migration of pancreatic cancer cells using CCK‐8, colony formation, and Transwell migration assays." (PMID 40751418, 2025). "We then investigated the role of CTHRC1 in CAFs in regulating pancreatic cancer cell proliferation." (PMID 40751418, 2025). "To further clarify the detailed mechanism of CTHRC1 in CAFs in pancreatic cancer, we found that LIF may be one of the key downstream molecules of CTHRC1 in CAFs regulating pancreatic cancer progression by RNA‐sequence results and database analysis." (PMID 40751418, 2025). "Additionally, EdU staining experiments demonstrated that knockdown of CTHRC1 in CAFs significantly inhibited pancreatic cancer cell proliferation and reduced cell numbers." (PMID 40751418, 2025). "Furthermore, CCK‐8, colony formation, and Transwell migration assays revealed that CTHRC1 in CAFs promotes pancreatic cancer cell proliferation and migration through LIF‐dependent regulation." (PMID 40751418, 2025). "Similarly, colony formation assays also showed that CTHRC1 in CAFs significantly enhanced pancreatic cancer cell colony formation ability." (PMID 40751418, 2025). "Therefore, these animal experiments indicate that CTHRC1 in CAFs promotes the proliferation, migration, and invasion of pancreatic cancer cells in vivo." (PMID 40751418, 2025). "Notably, HPSC‐CM exhibited significantly weaker activation of the STAT3 signaling pathway compared to CAFs‐CM, indicating that CTHRC1 in CAFs plays a critical role in activating this pathway in pancreatic cancer cells." (PMID 40751418, 2025). "Additionally, CTHRC1 knockdown CAFs significantly inhibited the invasion and metastasis of pancreatic cancer to the liver, intestine, and peritoneal cavity compared to the control group." (PMID 40751418, 2025). "Similarly, the scratch wound healing assay results also indicated that CTHRC1 in CAFs significantly promoted the migration and healing capacity of pancreatic cancer cells." (PMID 40751418, 2025). "Therefore, these experimental results suggest that CTHRC1 in CAFs significantly enhances the migration and invasion of pancreatic cancer cells." (PMID 40751418, 2025).
pancreatic cancer (continued). "To further explore the detailed molecular mechanism and signaling pathway by which CTHRC1 in CAFs regulates the progression of pancreatic cancer, we reviewed the literature and found that existing studies have confirmed that LIF mainly acts by activating the STAT3 signaling pathway." (PMID 40751418, 2025). "However, the regulatory role of CTHRC1 as a tumor microenvironment factor in pancreatic cancer is not well understood." (PMID 40751418, 2025). "Finally, to further explore and verify that CTHRC1 in CAFs activates the STAT3 signaling pathway in pancreatic cancer cells by regulating LIF, we cocultured CAFs‐CM with pancreatic cancer cells and added the LIF inhibitor EC330 at various concentrations." (PMID 40751418, 2025). "To explore whether CTHRC1 in pancreatic cancer CAFs has biological functions, we first constructed CAFs with CTHRC1 knockdown using siRNA transfection and lentiviral infection, and CAFs with CTHRC1 overexpression using lentiviral infection." (PMID 40751418, 2025). "Therefore, we conclude that CTHRC1 in CAFs enhances the epithelial‐mesenchymal transition ability of pancreatic cancer cells." (PMID 40751418, 2025). "Furthermore, within the same pancreatic tumor tissue, stromal cells showed a much higher CTHRC1 expression than in epithelium (cancer) cells." (PMID 37444482, 2023). "ECM-related genes upregulated by CTHRC1 were identified as follows: Pancreatic tumor mRNA correlation analyses were conducted between CTHRC1 and 20,530 genes, using the mRNA expression of pancreatic cancer tissue samples (n = 183) obtained from the TCGA PanCancer Atlas." (PMID 37444482, 2023). "Furthermore, CTHRC1 promoted pancreatic cancer cell proliferation through PSC activation to a greater extent than via direct stimulation." (PMID 37444482, 2023). "For the first time, this study demonstrated that pancreatic stellate cell (PSC) activation is a central mechanism of the pro-tumoral effects of CTHRC1 and elucidated the plasticity of the tumor microenvironment (TME) following CTHRC1-targeted pancreatic cancer treatment." (PMID 37444482, 2023). "Proof-of-concept studies using two different human pancreatic cancer mouse models are performed to investigate the effects of an anti-CTHRC1 monoclonal antibody (α-CTHRC1) treatment on ECM formation and the differentiation of cancer-associated fibroblasts (CAFs)." (PMID 37444482, 2023). "CTHRC1 regulates the expression of Ang-2 and promotes the angiogenesis of pancreatic tumors, while CTHRC1 secreted by osteoclasts may induce the development of cancerous bone lesions without mediating angiogenesis." (PMID 32848510, 2020). "The high level of CTHRC1 is connected with the progression and metastasis of pancreatic cancers through the activation of several key signaling molecules, including the steroid receptor coactivator (Src), FAK, paxillin, MEK, ERK, and Ras-related C3 botulinum toxin substrate 1 (Rac1)." (PMID 32848510, 2020). "Thus, in our experimental mouse model, a CTHRC1-neutralizing antibody exhibited therapeutic potential for treatment of pancreatic cancer through inhibition of vascular processes." (PMID 27686285, 2016). "Finally, using luminescence-based orthotopic pancreatic tumor xenograft models, we examined the therapeutic potential of the CTHRC1-neutralizing antibody." (PMID 27686285, 2016). "They found CTHRC1 increased motility and adhesiveness of pancreas cancer cells and HCC cells." (PMID 24841500, 2014). "CTHRC1 promoted growth of pancreatic tumor and metastatic spread of cancer cells to distant organs." (PMID 23922981, 2013). "Besides, they also found overexpression of CTHRC1 in pancreatic cancer cells resulted in increased motility and adhesiveness." (PMID 23922981, 2013). "Therefore, our results reveal the role of CTHRC1 in CAFs in pancreatic cancer, and the CTHRC1/LIF/STAT3 signaling axis may be a promising prognostic marker and therapeutic target for patients with pancreatic cancer." (PMID 40751418, 2025).
pancreatic cancer (continued). "Moreover, patients with high CTHRC1 expression had a significantly worse prognosis and higher recurrence and metastasis rates than those with low CTHRC1 expression, suggesting that CTHRC1 may play an important role in the development of pancreatic cancer." (PMID 40751418, 2025). "Key in vitro studies were conducted using both primary PSCs and immortalized PSCs to evaluate the potential differences in their responses to CTHRC1 because immortalized PSCs may differ considerably from primary PSCs in terms of their responses to pancreatic cancer cells." (PMID 37444482, 2023). "Collectively, our findings support the hypothesis that CTHRC1 induction of the Ang-2/Tie2 axis mediates the recruitment of TEMs, which are important for tumorigenesis and can be targeted to achieve effective antitumor responses in pancreatic cancers." (PMID 27686285, 2016). "To determine whether CTHRC1 affects tumor-adjacent cells, including immune cells and ECs, during pancreatic cancer development, we orthotopically injected CTHRC1-overexpressing MiaPaCA-2 (MiaPaCa-2/CTHRC1) cells, which had been transfected with a CTHRC1 expression plasmid, into NSG mice." (PMID 27686285, 2016). "The results showed that CTHRC1 knockdown in CAFs significantly downregulated the phosphorylation level of STAT3 and inhibited the activation of the STAT3 signaling pathway in pancreatic cancer cells." (PMID 40751418, 2025). "To further clarify the regulatory role of CTHRC1 on LIF in CAFs, we first examined the differential expression of LIF in CAFs, pancreatic cancer cell lines, and human pancreatic stellate cells (HPSCs)." (PMID 40751418, 2025). "CTHRC1 appears to be a potential therapeutic target for the treatment of pancreatic cancer, and the complexity and plasticity of the TME should be considered during the further development of anti-CTHRC1 treatments." (PMID 37444482, 2023). "[BACKGROUND] Collagen triple helix repeat containing-1 (CTHRC1) is a secreted protein that contributes to the progression of various cancers, including pancreatic cancer." (PMID 37444482, 2023). "We found that cancer stroma is the major source of CTHRC1 secretion in pancreatic cancer, and CTHRC1 regulates cancer extracellular matrix (ECM) remodeling by activating pancreatic stellate cells (PSCs), a main component of pancreatic cancer stroma." (PMID 37444482, 2023). "Our study aims to investigate the influences of CTHRC1 on pancreatic stellate cells (PSCs), a main source of ECM production in pancreatic cancer." (PMID 37444482, 2023). "CTHRC1 promoted tumor cell migration and invasion by activating Wnt/PCP signaling supported by activating Rac1 in pancreatic cancer, activating RhoA in HCC and activating both Rac1 and RhoA in GIST cells." (PMID 29285247, 2017). "We found RhoA is the most important small GTPase for CTHRC1-mediated HCC invasion and they found Rac1 accounts for the invasiveness in pancreatic cancer." (PMID 23922981, 2013). "Subsequent coculture of pancreatic cancer cells with CTHRC1‐knockdown CAFs‐CM and CTHRC1‐reconstituted‐overexpressing CAFs‐CM demonstrated that CAF‐derived CTHRC1 promotes epithelial‐mesenchymal transition and positively regulates STAT3 signaling pathway activation in cancer cells." (PMID 40751418, 2025). "The results showed that activated CAFs significantly promoted the phosphorylation of STAT3 in pancreatic cancer cells and induced activation of the STAT3 signaling pathway, suggesting that this may be related to the high expression of CTHRC1 in CAFs." (PMID 40751418, 2025). "This is because, consistent with previous studies, periostin expression was extremely low in pancreatic cancer cells and was not influenced by CTHRC1, and periostin was also shown not to influence the CTHRC1 levels of cancer cells." (PMID 37444482, 2023).